CD4 (CD4 molecule)
Diseases named in the same sentence as CD4 in open-access papers (continued):
Sharing a sentence is not in itself a finding about the gene and the disease.
HIV-1 infection (continued). "In summary, our study demonstrated that disruption of CCR5 using CRISPR/SaCas9 delivered by lentivirus in human primary CD4+ T cells resulted in T-cell prevention of HIV-1 infection and enrichment in humanized mice." (PMID 31186067, 2019). "Although the number of pDCs in peripheral blood drops during HIV-1 infection, in parallel with the drop of CD4+ T cells, the remaining pDCs maintain their phenotype and are, in fact, hyper activated." (PMID 31708924, 2019). "Several groups have reported both significantly lower frequencies of CD127+CD4+ T cells as well as lower CD127 expression levels on CD4+ T cells in untreated HIV-1 infection." (PMID 31507594, 2019). "Three days after in vitro autologous HIV-1 infection, CD4+ T cells were pretreated with lovastatin for 48 h." (PMID 31572371, 2019). "For HIV-1 infection and culture experiments, negatively enriched CD4+ T cells were prepared from 200 ml each of peripheral blood from three donors." (PMID 31036079, 2019). "The placenta-derived CECs, similar to the cord blood, significantly increased HIV-1 infection in autologous CD4+ T cells." (PMID 31772057, 2019). "The expression of PD-1 on non-classical CD14+CD16++ monocytes is positively correlated with the CD4/CD8 ratio during acute HIV-1 infection." (PMID 31651258, 2019). "Cord blood CD4+ T cells were isolated and made more permissible to HIV-1 infection by in vitro culture with exogenous IL-2 and phytohemagglutinin (PHA) stimulation." (PMID 31772057, 2019). "We also found that CECs isolated from the blood of anemic individuals enhance HIV-1 infection/replication when cocultured with autologous CD4+ T cells." (PMID 31772057, 2019). "Our results support these findings and indicate that SEA/rω-1, through interacting with DCs, can induce CD4+ lymphocytes responses with reduced proliferative/activation phenotypes with potential consequences for HIV-1 infection and/or replication." (PMID 31487324, 2019). "Another report studied HIV-1 infection in primary CD4+ T-cells and noted a small increase in overall HERV-K expression compared to uninfected cells." (PMID 31842941, 2019). "In the case of human CD4+ T lymphocytes, the permissiveness to HIV-1 infection depends on their cellular activation state." (PMID 31042779, 2019). "Due to the dichotomy in ROS production by CECs from IBD patients compared to healthy donors, we decided to perform HIV-1 infection assays using autologous CD4+ T cells and CECs from the cord blood of IBD patients." (PMID 31772057, 2019). "Human CD4+ T cells are the major target cells of HIV-1 infection, and thus most interesting to render HIV resistant." (PMID 30787394, 2019). "More recently, clinical trials have advanced a zinc finger nuclease that targets CCR5 and renders treated CD4+ T cells resistant to HIV-1 infection." (PMID 31455650, 2019). "Resting CD4+ TM cells have been proposed to be major reservoirs of latent HIV-1 infection, on the evidence of high levels of HIV-1 DNA content." (PMID 31036079, 2019). "TKO-BLT mice become reconstituted with high levels of multi-lineage human hematopoietic cells, are susceptible to HIV-1 infection, and develop hallmarks of human HIV-1 infection such as hyper-immune activation and CD4+ T cell depletion." (PMID 31792317, 2019). "The outcome of HIV-1 infection depends on both viral and host factors; the latter include features of cellular (CD4 and CD8 cells), humoral (B cells), and innate immunity (NK cells)." (PMID 30534128, 2018). "A low cytoplasmic dNTP concentration in macrophages (~130–250-fold lower than in resting or activated CD4+ T cells) was proposed to be a major obstacle to productive HIV-1 infection." (PMID 30423802, 2018). "HIV-1 infection is initiated by the binding and attachment of gp120 to CD4, which induces a series of conformational changes in gp120 that consequently expose its third variable (V3) loop for specific recognition of a coreceptor, either CCR5 or CXCR4." (PMID 30463393, 2018).
HIV-1 infection (continued). "Näslund and group demonstrated that exosomes from breast milk inhibit HIV-1 infection of dendritic cells and subsequent viral transfer to CD4+ T cells." (PMID 29429034, 2018). "A potential link between miRNA expression levels and the recalcitrance of resting memory CD4+ T-cells to HIV-1 infection has also been reported." (PMID 29510515, 2018). "For instance, Tfh cells expressing CD57, show a significantly higher frequency of HIV-1 infection compared with extrafollicular CD4 T cells and transcriptional signatures that show differences when compared to CD57-." (PMID 30081906, 2018). "The change of miRNA profiles in CD4+ T cells is even more closely correlated with disease progression since the CD4+ T cells are the main targets of HIV-1 infection." (PMID 30619232, 2018). "We found that expression of CD95 was significantly up-regulated in both CD4+ and CD4- ILC1s from patients with chronic HIV-1 infection compared with HC subjects." (PMID 29304123, 2018). "Both the CD4+ T-cell number and purity isolated from splenic tissues were normalized between the SIVcpz and HIV-1 infection groups." (PMID 29615603, 2018). "In summary, we identified subset- and tissue-dependent heterogeneity of ILC1s and provided evidence to show that CD4+ ILC1s are a novel target for HIV-1 infection." (PMID 29304123, 2018). "In HIV-1 infection, the number of pDCs as well as their function is decreased simultaneously with CD4+ T cell population." (PMID 29597250, 2018). "In support of this concept, several observational studies in patients with chronic HIV-1 infection have demonstrated higher CD4 counts and/or lower HIV-1 viral loads in those with versus those without helminth co-infection." (PMID 29965987, 2018). "We thus conclude that chronic HIV-1 infection impaired the ability of the remaining ILC1s, including CD4+ ILC1s, to produce cytokines." (PMID 29304123, 2018). "A strong reason to use a spatial model when estimating the risk of HIV-1 infection in HSV-2-affected tissue is that there is likely to be a correlation between the location of tissue damage and the location of CD4+ T cells." (PMID 29698393, 2018). "Upon HIV-1 infection of CD4+ T cells, the HIV-1 capsid is delivered into the cytoplasm allowing reverse transcription of the viral RNA into DNA, a step that is strictly dependent on the availability of the dNTPs." (PMID 30574147, 2018). "Due to the importance of the cellular immune response against HIV-1 infection, the development of vaccine candidates targeting conserved T lymphocyte epitopes, especially of CD4+ T cells, has become relevant." (PMID 29467764, 2018). "Taken together, our observations provide new insight into the possible role of T cell activation in preventing CD4+ T cell depletion during acute HIV-1 infection." (PMID 29636753, 2018). "Fibroblastic reticular cells (FRCs) are stromal cells in secondary lymphoid organs, the major sites for HIV-1 infection of CD4+ T cells." (PMID 29934525, 2018). "The cellular route of HIV-1 entry for productive infection in CD4+ host cells is a fundamental question for the molecular understanding of HIV-1 infection and transmission." (PMID 31058179, 2018). "The levels of miR-9 in CD4+ T cells from individuals with chronic HIV-1 infection are lower than those in healthy individuals or LTNPs." (PMID 30619232, 2018). "Although these anti-3S Abs do not neutralize the virus, they are produced in humans at early stages of HIV-1 infection, and inversely correlate with CD4 cell-count decrease." (PMID 29662026, 2018). "Despite CD4+ T cells are critical for control of viral infections, less is known about their co-expression pattern of inhibitory receptor in HIV-1 infection and in relation to healthy subjects." (PMID 29403500, 2018). "In 1996, Samson and colleagues reported that a 32-base-pair deletion mutant of CCR5 (CCR5Δ32) confers resistance to HIV-1 infection in CD4+ cells." (PMID 30619107, 2018).
HIV-1 infection (continued). "The relationship between CD30 expression and immunological phenotypes in the setting of HIV-1 infection was determined on fresh peripheral blood CD4+ T cells isolated from HIV-1-infected and uninfected individuals." (PMID 29470552, 2018). "To prepare for detailed mechanistic studies, we performed a similar assessment of the inhibitory role of SUN2 on HIV-1 infection in the Jurkat CD4+ T-cell line." (PMID 29717016, 2018). "CD4+ T-cell decline in the peripheral blood of hu-BLT mice infected with HIV-1 was observed a few weeks post-HIV-1 infection, which is consistent with previous reports." (PMID 29615603, 2018). "In order to address this question, we conducted shRNA-mediated knockdown of UPF1 in primary CD4+ T cells and observed the effects on vRNA levels and pr55Gag expression upon HIV-1 infection by FISH-Flow." (PMID 29954456, 2018). "We showed that HIV-1 infection decreases the expression of a cellular miRNA let-7i in CD4+ T cells by attenuating the transcription of its precursor." (PMID 29426337, 2018). "These are promising findings that will lead to new research aimed at further understanding the role of the CD300a inhibitory receptor in CD4+ T lymphocytes during chronic HIV-1 infection." (PMID 30083165, 2018). "Treatment of unactivated CD4+ T-cells with MIF-treated HIV-infected MDM-derived culture supernatants led to enhanced permissiveness to HIV-1 infection." (PMID 29997630, 2018). "To investigate the effect of HIV-1 infection on the human immune system, we analyzed T cells (CD4+ and CD8+) in the peripheral blood, spleen and liver." (PMID 29361613, 2018). "Our mathematical model reveals a threshold condition in which HIV-1 infection is dependent upon the rate that CD4 T cells traffic between compartments." (PMID 29499057, 2018). "We discovered that chronic HIV-1 infection significantly up-regulated active caspase-3 expression in both CD4+ and CD4- ILC1s." (PMID 29304123, 2018). "Another member of the cellular miR-34 family, the miR-34c-5p was also recently shown to promote HIV-1 infection in CD4+ T-cells." (PMID 29510515, 2018). "HIV-1 infection leads to progressive CD4+ T cell depletion in both peripheral blood and lymphoid tissues." (PMID 29725337, 2018). "Further analysis indicated that the percentage of both CD4+ and CD4- ILC1s was reduced during chronic HIV-1 infection." (PMID 29304123, 2018). "The route of HIV-1 entry for productive infection in CD4+ host cells is a fundamental question for the molecular understanding of HIV-1 infection and transmission." (PMID 31058179, 2018). "SAMHD1 is a dGTP-dependent deoxynucleoside triphosphohydrolase that reduces intracellular dNTPs below the levels required for HIV-1 reverse transcription, thereby blocking HIV-1 infection in resting CD4+ T-cells." (PMID 29337866, 2018). "These bioactivity data also provide evidence that 3 is a viable lead compound for developing new ligands to inhibit HIV-1 infection via CD4." (PMID 30463393, 2018). "The p70-S6K1 and MK2 kinases identified by KSEA and shown here to be required for optimal HIV-1 infection of primary CD4+ T cells are known regulators of protein translation and cytoskeletal reorganization, respectively." (PMID 29970186, 2018). "As the number of tissue-resident CD4+ T cells is thought to affect the risk of HIV-1 acquisition, this result indicates a deficiency of HSV-2 antiviral strategies in preventing HIV-1 infection." (PMID 29698393, 2018). "Altogether, these results indicate that HIV-1 infection induces an increase on the expression of CD300a inhibitory receptor on CD4+ T cells that otherwise already express the checkpoint PD-1." (PMID 30083165, 2018). "HIV-1 infection induces a progressive and quantitative decline in CD4+ T cell responses, and this finally leads to AIDS." (PMID 30463393, 2018).
HIV-1 infection (continued). "Our findings reveal a novel pathway that the HIV-1 infection-induced suppression of the let-7i/IL-2 axis contributes to CD4+ T cell death." (PMID 29426337, 2018). "We next interrogated the roles of endogenous IFITM proteins in modulating HIV-1 infection in primary human CD4+ PBMCs and purified T lymphocytes." (PMID 30087232, 2018). "The group of patients treated with IRC were slightly older, with a lower nadir CD4 and with greater time of HIV-1-infection with respect to other treatments groups." (PMID 30067738, 2018). "Taken together, the results from CD4 competitive binding and anti-HIV-1 infection assays showed that 3 is a promising new lead compound for the effective inhibition of HIV-1 entry via CD4." (PMID 30463393, 2018). "In fact, the calculated dNTP concentrations in cells (mainly) refractory to HIV-1 infection, macrophages and resting CD4+ T cells, are lower than the measured dNTP levels in the G1 phase in HeLa cells." (PMID 29884836, 2018). "Conversely, NBD-556 and its analogs, as CD4-mimics, were designed to target the Phe43 cavity of gp120, thereby, inhibiting the gp120/CD4 interaction and HIV-1 infection." (PMID 30463393, 2018). "These authors further reported that the miR-146a upregulation by AMD3100 treatment or PLZF silencing decreases CXCR4 protein expression and prevents HIV-1 infection in monocytic cell line and CD4+ T lymphocytes." (PMID 29426337, 2018). "Strikingly, as HeLa or activated primary CD4+ T cells enter the G1 phase, pronounced reduction of RT products is observed upon HIV-1 infection dependent on the presence of dephosphorylated SAMHD1." (PMID 29884836, 2018). "By fitting linear planes to the data, the probability of HIV-1 infection can be expressed as a simple function of the CD4+ T cell concentration and the amount of tissue damage within the simulation region at the time of exposure." (PMID 29698393, 2018). "Schistosoma co-infection was negatively associated with the log10 of viral load after adjustment for Schistosoma intensity as measured by CAA, CD4 counts at time of testing, and duration of HIV-1 infection (β = −0.7[−1.3;−0.1], p = 0.022)." (PMID 30237799, 2018). "For instance, IFN-α significantly induces A3G expression in human primary resting CD4+ T cells, macrophages, DCs, and endothelial cells in the brain restricting HIV-1 infection." (PMID 30574147, 2018). "The lower CD4 count in HIV-infected patients with ADC is the consequence of the longer duration of HIV-1 infection with worsening immunodeficiency, which was frequent in the pre-cART times." (PMID 30298049, 2018). "CD4+ T-cell depletion and immune activation are the hallmarks of human HIV-1 infection and disease progression." (PMID 29615603, 2018). "Our research provides us a new insight into the role of T cell immune activation in acute HIV-1 infection in CD4+ T cell depletion over time." (PMID 29636753, 2018). "Cryptococcal pneumonia is an underrecognized condition and should be considered in the differential of patients with HIV-1 infection and low CD4 count who develop respiratory symptoms." (PMID 29379704, 2018). "We find that the risk of HIV-1 infection is dependent on three factors: the amount of HIV-1 the patient is exposed to, the severity of HSV-2 lesions, and the number of CD4+ T immune cells in the genital mucosa." (PMID 29698393, 2018). "Research has focused on the impact of cholesterol content in virion envelopes on HIV-1 infection and pathogenesis and characterized the association of cholesterol with binding, entry, and budding of HIV-1 particles from target CD4+ T cells." (PMID 29643243, 2018). "To explore if L-selectin binding affected HIV-1 infection, we transfected human L-selectin cDNA into REV-CEM, a CD4+ T-cell line susceptible to X4-tropic HIV infections." (PMID 30026537, 2018).
HIV-1 infection (continued). "Cell-to-cell fusion between infected CD4+ T cells, or between infected and uninfected CD4+ T cells, has been initially proposed to be another mechanism for HIV-1 infection and dissemination between T cells." (PMID 29515578, 2018). "Activation of CD4+ T-cells is a prerequisite for productive HIV-1 infection and entails substantial transcriptional changes, including alterations in cellular miRNA expression." (PMID 29510515, 2018). "We estimate the relative importance of decreased tissue damage versus decreased CD4+ cell presence in determining the effectiveness of pritelivir in reducing HIV-1 infection." (PMID 29698393, 2018). "To examine if L-selectin affected HIV-1 infection of primary CD4+ T cells, we carried out HIV-1BAL infection of CD8-depleted PBMC in the presence of EDTA, a calcium chelator that inhibited L-selectin binding to gp120." (PMID 30026537, 2018). "In vitro, epigenetic modifications in PBMC or primary CD4+ T cells can be detected as early as 36 hours after HIV-1 infection." (PMID 29710792, 2018). "IFN-γ has been shown to induce both early and late blocks to HIV-1 infection in CD4+ T cells, macrophages and a number of commonly used cell lines." (PMID 30132758, 2018). "Although high level of CD4+ T cell activation in early HIV-1 infection stage is beneficial for CD4+ T cell preservation, we proposed that this CD4+ T cell activation belongs to a homeostatic response to HIV-1." (PMID 29636753, 2018). "In contrast to HIV-1 infection of PBMCs, the LPAC model does not require prior exogenous mitogen stimulation to obtain reproducible CCR5-tropic HIV-1 infection and CD4+ T cell death." (PMID 28241075, 2017). "While in the case of HIV-1 infection there is a steady decline in CD4+ T-cell count, in HIV-2 infection, the decline is much slower and viremia levels are lower at any stage of the disease." (PMID 28588579, 2017). "Within the first year of HIV-1 infection, preferential depletion of gut CD4+ T cell subsets that produce IL17 (Th17) and IL22 (Th22) were documented." (PMID 28241075, 2017). "Second, HIV-1 infection of gut CD4+ T cells downregulated HIV-1-reactome (cofactor) genes at 4 dpi, mirroring data on HIV-1 infection of SupT1 cell lines at 1 dpi." (PMID 28241075, 2017). "While HIV-1 infection of CD4+ T lymphocytes, perivascular macrophages and microglia is well recognized, infection of astrocytes remains unresolved." (PMID 29084769, 2017). "Understanding the down-regulation of cyclin F in the context of HIV-1 infection in CD4+ T cells is therefore important and necessitates further studies." (PMID 28184007, 2017). "In this study, we used a humanized mouse model to show that HIV-1 infection induces immune activation and augments the expression of endogenous A3H in human CD4+ T cells." (PMID 28475648, 2017). "To investigate the expression of aNKR ligands on CD4+ T cells and the modulatory effects of HIV-1 infection on aNKR expression, we used 4 Ab panels specific for aNKR ligands." (PMID 29023371, 2017). "Jurkat CD4 T cells, a well-characterized model of HIV-1 infection and T cell signaling, were labeled using either “heavy” (R10K8) or “light” (R0K0) amino acids for at least six doublings." (PMID 28122231, 2017). "In contrast to these studies, the Nabel lab used PBMC-derived primary CD4+ T cells and found that, in these cells, HIV-1 induced cell death was associated with productive HIV-1 infection and dependent on integration." (PMID 29056936, 2017). "In the case of HIV-1 infection, the levels of CD4 in macrophages appear to have a direct impact on the susceptibility of these cells to HIV-1 infection as well as on the properties that CCR5-tropic Env need to have to mediate viral entry in macrophages." (PMID 29301198, 2017). "Our group and others reported that IL17-producing CD4+ T cells (Th17), and in particular, those producing IFNγ and IL17 (Th1/17), were highly susceptible to HIV-1 infection in vitro." (PMID 28241075, 2017).